RBPJ (recombination signal binding protein for immunoglobulin kappa J region)
Diseases named in the same sentence as RBPJ in open-access papers (continued):
Sharing a sentence is not in itself a finding about the gene and the disease.
laryngeal carcinoma (5 papers, 2018 to 2024). Carcinoma that arises from the laryngeal epithelium. "AFAP1-AS1/miR-320a/RBPJ axis is reported to be associated with stemness and chemoresistance to cisplatin in laryngeal carcinoma." (PMID 39574469, 2024). "qRT‐PCR of 24 human laryngeal carcinoma specimens revealed that endogenous expression of miR‐320a was negatively associated with the expression of the RBPJ." (PMID 29971915, 2018). "For example, AFAP1-AS1 is discovered to be significantly highly expressed in laryngeal cancer tissues, and by regulating the miR-320a/RBPJ axis, AFAP1-AS1 enhances the cancer cells’ stemness and resistance to chemotherapy." (PMID 33926489, 2021). "Ultimately, we found not only that AFAP1‐AS1 increases laryngeal carcinoma stemness and chemoresistance, but also that it does so by regulating miR‐320a activity and RBPJ expression." (PMID 29971915, 2018). "In this study, we have determined for the first time that RBPJ is crucial for the regulation of laryngeal carcinoma cell stemness and chemoresistance." (PMID 29971915, 2018). "As we expected, overexpression of RBPJ rescued tumour sphere number and drug‐induced apoptosis of laryngeal carcinoma cells." (PMID 29971915, 2018). "Moreover, as a downstream target of long non-coding RNA AFAP1-AS1, the low expression of miR-320a promoted the stemness and DDP chemoresistance of laryngeal carcinoma cells by negative regulation of RBPJ mRNA and protein." (PMID 35444548, 2022). "To analyse whether AFAP1‐AS1 regulates laryngeal carcinoma cells through miR‐320a‐mediated RBPJ, we increased RBPJ expression in AFAP1‐AS1 silencing HEp‐2 cells." (PMID 29971915, 2018). "The further use of DIANA Tools and a number of cell biology assays allowed us to determine conclusively that miR‐320a targets RBPJ and that AFAP1‐AS1 increases RBPJ expression by negatively regulating miR‐320a, thereby giving rise to laryngeal carcinoma's stemness and chemoresistance." (PMID 29971915, 2018). "Furthermore, we investigated the role of RBPJ in laryngeal carcinoma cell development." (PMID 29971915, 2018). "In laryngeal carcinoma cells, AFAP1-AS1 can upregulate recombination signal binding protein for immunoglobulin kappa J region (RBPJ) expression by negative regulation of hsa-miR-320a-3p, and enforced expression of RBPJ could reduce the stemness and chemoresistance inhibited by AFAP1-AS1 silencing." (PMID 34071109, 2021).
myocardial infarction (5 papers, 2016 to 2021). Gross necrosis of the myocardium, as a result of interruption of the blood supply to the area, as in coronary thrombosis. "Furthermore, the loss of RBPJ in cardiomyocytes increased hypoxia tolerance, improved heart function and decreased pathological remodelling after myocardial infarction, suggesting that inhibiting RBPJ might be therapeutic for ischaemic injury." (PMID 27357444, 2016). "Nuclear-localized and faint cytoplasmic RBPJ is readily detected in the adult heart, both in cardiomyocytes and non-myocytes, and its level does not change substantially following either chronic pressure overload by thoracic aortic constriction (TAC) or myocardial infarction." (PMID 27357444, 2016).
brain tumor (4 papers, 2017 to 2022). "Since malignant-brain-tumor (MBT) containing proteins were described to bind to methylated lysine residues, it is possible that lysine methylation of RBPJ also plays a role in the recruitment mechanism." (PMID 34332624, 2021).
prostate carcinoma (4 papers, 2015 to 2024). A carcinoma that arises from epithelial cells of the prostate gland. "Using a Notch-sensitive Recombination signal binding protein for immunoglobulin kappa J region (RBPJ) reporter assay, we found that basal levels of Notch signalling were significantly lower in prostate cancer cells compared to benign cells." (PMID 25864518, 2015). "In addition, It has been reported that overexpressed Jagged1 enhances prostate cancer cell proliferation by interacting with AR, thereby promoting the development of prostate cancer, and silencing of RBPJ reduces the expression of the AR and its target genes." (PMID 38538986, 2024).
Alagille syndrome (3 papers, 2022 to 2025). "Lastly, an unanswered question is how variants in RBPJ, which is the sole transcription factor downstream of all NOTCH receptors, cause an N1/DLL4 syndrome (AOS) but not an N2/JAG1 syndrome (Alagille syndrome)." (PMID 41055965, 2025).
bladder cancer (3 papers, 2022 to 2025). "For instance, TRIM25-mediated ubiquitination accelerates RBPJ degradation via proteasome in bladder cancer validated by immunoprecipitation without further studying the binding residues." (PMID 40723303, 2025). "Similarly, in bladder cancer cells, overexpressed RITA1 induced degradation of RBPJ by recruiting the E3 ligase TRIM25." (PMID 36293193, 2022).
cholestasis (3 papers, 2016 to 2024). Impairment of the bile flow caused by obstruction within the liver, or outside the liver in the bile duct system. "We claim this mechanism as an important driver for liver regeneration upon RBPJ loss-induced cholestasis." (PMID 30501048, 2018). "In conclusion, we suppose the YAP activation as a mechanism for a compensatory liver regeneration after RBPJ ablation induced cholestasis." (PMID 30501048, 2018). "We observed abnormalities in liver development after RBPJ-KO, demonstrating in the perinatal period, that the development of the biliary tree was abnormal and cholestasis emerged." (PMID 26951801, 2016). "After injecting Microfil, we found that the intrahepatic bile ducts in the RBPJ-KO mice were highly disordered, consistent with their biochemical cholestasis." (PMID 26951801, 2016). "The co-treatment of GCA and VP gradually reduced expression levels of Sox9 and the YAP target genes Cyr61, Ctgf, Afp and Ankrd1 indicating a direct link between cholestasis mediated expression of Sox9 through activation of YAP, which is independent of RBPJ." (PMID 30501048, 2018).
COVID-19 (3 papers, 2022 to 2025). A disease caused by infection with severe acute respiratory syndrome coronavirus 2. "The expression of RBPJ is of particular interest, as it is linked to TH17 cell pathogenicity, suggesting a role of pathogenic TH17 cells in COVID-19." (PMID 37730638, 2023).
lymphoma (3 papers, 2014 to 2018). A malignant (clonal) proliferation of B- lymphocytes or T- lymphocytes which involves the lymph nodes, bone marrow and/or extranodal sites. "RBPJ-deficient splenic NKp46+NK1.1+ cells showed significantly increased lytic abilities on YAC-1 mouse lymphoma cells that correlated with an increase frequency of cells capable to produce TNFa and IFNg." (PMID 29930552, 2018).
Merkel cell carcinoma (3 papers, 2019 to 2025). "Preliminary research about how aberrant miRNA expression can influence neuroendocrine cell behaviours showed a direct post-transcriptional repression of NOTCH2 and RBPJ proteins operated by miR-375 (microRNA 375) in Merkel cell carcinoma (MCC), a rare cutaneous neuroendocrine malignancy." (PMID 31443481, 2019).
osteosarcoma (3 papers, 2009 to 2022). A usually aggressive malignant bone-forming mesenchymal neoplasm, predominantly affecting adolescents and young adults. "Circ_0060428 was shown to promote osteosarcoma cell proliferation through the miR-375/RBPJ axis." (PMID 35383130, 2022).
renal carcinoma (3 papers, 2022 to 2023). A carcinoma arising from the epithelium of the renal parenchyma or the renal pelvis. "In summary, our results demonstrate that the RBPJ/DAPK3/UBE3A/PBRM1/p21 signaling pathway regulated the sensitivity of renal cancer cells to CDK4/6 inhibitors." (PMID 35368029, 2022). "In summary, we not only revealed a novel RBPJ/DAPK3/UBE3A/PBRM1/p21 signaling axis but also identified a combination strategy for overcoming the resistance of renal cancer cells to CDK4/6 inhibitors." (PMID 35368029, 2022). "Moreover, the RBPJ/DAPK3/UBE3A/PBRM1/p21 axis induced increased sensitivity of renal cancer cells to CDK4/6 inhibitors." (PMID 37385985, 2023). "Therefore, we not only revealed a novel RBPJ/DAPK3/UBE3A/PBRM1/p21 axis but also identified a combination strategy for overcoming the resistance of renal cancer cells to CDK4/6 inhibitors." (PMID 35368029, 2022). "Finally, we demonstrated that the RBPJ/DAPK3/UBE3A/PBRM1/p21 axis contributed to the sensitivity of renal cancer cells to CDK4/6 inhibitors." (PMID 35368029, 2022). "Moreover, our data suggest that the RBPJ/DAPK3/UBE3A/PBRM1/p21 axis modulated the sensitivity of renal cancer cells to CDK4/6 inhibitors." (PMID 35368029, 2022). "Taken together, these data suggest that RBPJ acts as a transcription factor of DAPK3 and regulates PBRM1 in renal cancer cells." (PMID 35368029, 2022). "In addition, in combination with RBPJ inhibitors, CDK4/6 inhibitors showed synergistically enhanced effects on renal cancer cells." (PMID 35368029, 2022). "However, knocking down RBPJ downregulated the protein and mRNA levels of DAPK3 in renal cancer cells." (PMID 35368029, 2022). "In combination with RBPJ inhibitors, CDK4/6 inhibitors synergistically enhanced renal cancer cells." (PMID 35368029, 2022).
viral infection (3 papers, 2016 to 2024). "The primary B cell infection with this virus unequivocally demonstrated that the RBPJ BM EBNA3C virus is completely unable to repress ADAM28, ADAMDEC1 and COBLL1, providing compelling evidence that the EBNA3C:RBPJ interaction is essential in the context of viral infection." (PMID 26751214, 2016). "In conclusion, these results showed that the ability of EBNA3C to interact with RBPJ is not only essential for repression in transient reporter assays, but also for the repression of the endogenous COBLL1 and ADAM28-ADAMDEC1 locus in the context of viral infection." (PMID 26751214, 2016).
breast tumor (2 papers, 2013 to 2022). "The terminal differentiation of macrophages to TAMs depends on RBPJ; RBPJ-expressing TAMs are consistent with increase of PD1+ CD8+ T-cells and encourage breast tumor burden." (PMID 35682974, 2022).
cervical cancer (2 papers, 2022 to 2025). A primary or metastatic malignant neoplasm involving the cervix.
Diabetic Nephropathy (2 papers, 2017 to 2022). "The conditional deletion of RBPJ specifically in podocytes in mice with diabetic nephropathy was associated with reduced podocyte apoptosis." (PMID 35215234, 2022).
Intellectual disability (2 papers, 2013 to 2023). "It should be noted that both MEF2C and RBPJ have been associated with intellectual disability and seizure disorders, matching the SOX18 E137K Geno2MP neurological phenotypes." (PMID 36672963, 2023).
latent infection (2 papers, 2012 to 2021). "RBPJ interaction with replication and transcription activator (RTA) is essential for lytic replication, while the interaction with latency-associated nuclear antigen (LANA) facilitates latent infection." (PMID 35069510, 2021).
liver disease (2 papers, 2020 to 2022). "Therefore, the multifaceted effect of RBPJ expressed in macrophages during liver diseases are associated with the different of clinical disease stages." (PMID 36276639, 2022). "We hypothesized that inhibition of RBPJ in the early stage of disease is a possible therapeutic approach to fibrotic liver diseases, while the inhibition of RBPJ in the late stage of the disease may lead to unsatisfactory treatment effect." (PMID 36276639, 2022).
mantle cell lymphoma (2 papers, 2021 to 2022). Mantle cell lymphoma is a rare form of malignant non-Hodgkin lymphoma affecting B lymphocytes in the lymph nodes in a region called the ``mantle zone''. "Upon further analysis of this published data set generated in the mantle cell lymphoma cell line Rec-1, we found a consensus RBPj site within intron 2 of the IL21r locus, which showed strong binding of RBPj and MAML, as well as γ-secretase inhibitor–sensitive (GSI-sensitive) Notch1 binding." (PMID 35349492, 2022).
Splenomegaly (2 papers, 2020). Abnormal increased size of the spleen. "While it is known that RBPJ deficiencies can lead to splenomegaly, lymphadenopathy, the spontaneous formation of germinal centers, and a TH2-associated immunoglobulin class switch, RBPJ’s contributions to cancer remain poorly understood." (PMID 32039830, 2020).
Achalasia (1 paper, 2023). A disorder of esophageal motility characterized by the inability of the lower esophageal sphincter to relax during swallowing and by inadequate or lacking peristalsis in the lower half of the body of the esophagus. "Among these DEGs, ZNF683, important for the differentiation and maintenance of TRM39, and RBPJ, central to Notch signaling and maintenance of TRM40, were highly expressed in TRM, which might explain the high infiltration of TRM in achalasia." (PMID 37542039, 2023).
acute monocytic leukemia (1 paper, 2021). Acute monoblastic leukemia (AML-M5), is one of the most common subtypes of acute myeloid leukemia (AML) that is either comprised of more than 80% of monoblasts (AML-M5a) or 30-80% monoblasts with (pro)monocytic differentiation (AML-M5b). "In THP-1 cells (acute monocytic leukemia), RBPJL expression was detectable, but less than that of RBPJ." (PMID 34638511, 2021).
acute promyelocytic leukemia (1 paper, 2021). An aggressive form of acute myeloid leukemia (AML), characterized by arrest of leukocyte differentiation at the promyelocyte stage, due to a specific chromosomal translocation t(15;17) in myeloid cells. "Surprisingly, in selected myeloid leukemia cell lines U937 (histiocytic lymphoma) and NB-4 (acute promyelocytic leukemia) we found RBPJL expression levels comparable to that of RBPJ." (PMID 34638511, 2021).
astrocytomas (1 paper, 2018). "RBPJ aberrations were mutually exclusive with NOTCH1 mutations and were not present in IDH mutant or IDH wild-type astrocytomas." (PMID 30417117, 2018).
embryonal carcinoma (1 paper, 2014). A non-seminomatous malignant germ cell tumor characterized by the presence of large germ cells with abundant cytoplasm resembling epithelial cells, geographic necrosis, high mitotic activity, and pseudoglandular and pseudopapillary structures formation. "Genome-wide analysis in the murine embryonal-carcinoma cell line F9 revealed that roughly 60% of the sites occupied by RBPJ in asynchronous cells were also occupied in mitotic cells." (PMID 24603501, 2014). "To examine the variability of RBPJ occupancy between different cell lines, we have directly compared our data obtained with the embryonal carcinoma cell line F9, to the published data sets obtained with the murine TLL cell lines, T6E and G4A2." (PMID 24603501, 2014). "Our genome-wide studies in the murine embryonal carcinoma cell line F9 revealed that approximately 60% of the RBPJ occupancy sites in cycling cells are maintained on mitotic chromatin, and this accounts for approximately 80% of the total RBPJ occupancy sites observed in mitotic cells." (PMID 24603501, 2014). "It is possible that a functional relationship between RBPJ and CTCF is restricted to developmentally early cells, represented by the F9 embryonal carcinoma cell line, in which both CTCF and RBPJ play prominent roles." (PMID 24603501, 2014).
endometrial cancer (1 paper, 2026). Primary or metastatic malignant neoplasm involving the endometrium (mucous membrane that lines the endometrial cavity). "In patients with endometrial cancer, the lysine acetyltransferase KAT2B can bind to the transcriptional repressor RBPJ, simultaneously increasing the acetylation level of RBPJ." (PMID 41513612, 2026).
experimental autoimmune encephalomyelitis (1 paper, 2021). An autoimmune demyelinating disease of the central nervous system that is produced experimentally in animals by the injection of homogenized brain or spinal cord in Freund's adjuvant. "We also observed that this cluster has high expression of the transcriptional factor RBPJ, which has been shown to be fundamental for the pathogenicity of TH17 cells in an experimental autoimmune encephalomyelitis mouse model." (PMID 33622974, 2021).
hemangioma (1 paper, 2022). A benign vascular lesion characterized by the formation of capillary-sized or cavernous vascular channels. "To assess the physiological relevance of RBPJ in the context of hemangioma, we analyzed both RBPJ and SOX18 expression patterns in formalin-fixed, paraffin-embedded (FFPE) sections from patients with IH." (PMID 34874911, 2022).
Influenza infection (1 paper, 2011). "Influenza infection might therefore induce the over-expression of both inhibitors (BLC6 and RBPJ) and activators (ISGF3) (data not shown)." (PMID 21651802, 2011).
intrahepatic cholestasis (1 paper, 2016). A cholestasis characterized by impairment of the bile flow caused by obstruction located in the liver. "The RBPJ-KO mouse also showed more biliary abnormalities, intrahepatic cholestasis, and peri-portal necrosis compared to littermate controls." (PMID 26951801, 2016). "We also established that the mortality of the RBPJ-KO mice increased significantly, compared with the heterozygotes, and H&E staining revealed greater necrosis and intrahepatic cholestasis." (PMID 26951801, 2016). "Concordantly, we observed that blocking Notch–RBPJ signaling during development leads to excessive liver parenchymal regeneration (presumably due to differentiation of hepatoblasts into hepatocytes) along with disordered regeneration of the bile ducts and intrahepatic cholestasis." (PMID 26951801, 2016). "Furthermore, RBPJ-KO mice showed biliary abnormalities, intrahepatic cholestasis, and peri-portal necrosis that was absent in littermate controls." (PMID 26951801, 2016).
lipoma (1 paper, 2024). A benign, usually painless, well-circumscribed lipomatous tumor composed of adipose tissue. "In addition to known RITA partners, such as RBP-J (recombination signal binding protein for immunoglobulin kappa J region) and LPP (lipoma-preferred partner), PRC1, NUMA1 (nuclear mitotic apparatus protein 1) and MAP1B (microtubule-associated protein 1B) were among the RITA interaction partners." (PMID 39839673, 2024).
Miscarriage (1 paper, 2024). A pregnancy that ends at a stage in which the fetus is incapable of surviving on its own, defined as the spontaneous loss of a fetus before the 22th week of pregnancy. "Loss of RBPJ enhances ERα activity, resulting in excessive response to E2 and inducing abnormal implantation and mid-to-late pregnancy miscarriage." (PMID 39364135, 2024).
muscular dystrophy (1 paper, 2022). Muscular dystrophy (MD) refers to a group of more than 30 genetic diseases characterized by progressive weakness and degeneration of the skeletal muscles that control movement. "Therefore, RBPJ is necessary for embryonic development and it will lead to muscular hypoplasia and muscular dystrophy when RBPJ is deficient." (PMID 35454249, 2022).
myocarditis (1 paper, 2024). Myocarditis is a condition that is characterized by inflammation of the heart muscle (myocardium). "Although RBPJ wasn’t involved in the pathways identified through GO or KEGG analysis, AAbs against RBPJ were detected in the sera of all patients with ICI myocarditis." (PMID 39324142, 2024). "Further research is needed to determine whether anti-RBPJ AAbs can be used as biomarkers for ICI myocarditis and whether they are involved in the pathogenesis of ICI myocarditis." (PMID 39324142, 2024).